AIRE (autoimmune regulator)
Diseases named in the same sentence as AIRE in open-access papers (continued):
Sharing a sentence is not in itself a finding about the gene and the disease.
tumor (19 papers, 1990 to 2025). "Epidemiological study shows that AIRE gene expression is strongly associated with tumor prognosis in ER positive breast cancer patients." (PMID 31641374, 2019). "APS-1 patients carry AIRE mutations that lead to autoantibodies against IL-17A/F, IL-22 and type I interferons (IFN-α/ω) and impair Th17 antifungal immunity and tumor surveillance." (PMID 41009535, 2025). "Enhanced colony formation capability and upregulated stemness-associated gene expression were observed in AIRE-overexpressed tumor cells." (PMID 37369642, 2023). "Here, we required an allograft mouse model which is generated by using the tumor cell lines obtained from the identical genetic background as we needed to generate tumor model in AIRE+/+ and AIRE−/− mice." (PMID 29795364, 2018). "AIRE being a regulator of IL-6 malignancy gene shows lymphadenopathy and inflammation in AIRE+/+ mice and only a small benign tumor is observed AIRE−/− mice." (PMID 29795364, 2018). "Here, in this study, we have found AIRE as a host transcription factor which promotes tumor by acting as a transcriptional inducer of the IL-6 gene." (PMID 29795364, 2018). "KRT17 also modulates the expression of the transcriptional regulator AIRE (autoimmune regulator) in diseased epithelia, which induces the expression of proinflammatory cytokines and supports tumor progression." (PMID 27512993, 2016). "AIRE is also involved in the development of tumor-associated Foxp3 + regulatory T cells (Tregs), which do not respond to tumor-specific antigens." (PMID 31641374, 2019). "Subcutaneous injection of TRAMP-C1 cells resulted in no visible tumor in female mice, big palpable benign tumors in male AIRE+/+ mice after 40 days of initial injection whereas to our surprise we observed small localized tumor growth in case of male AIRE−/− mice after 55 days postinjection." (PMID 29795364, 2018). "The model foreign antigen gp33, an epitope derived from the LCMV glycoprotein, was included to address whether tumour rejection by AIRE−/− mice could be due to a generally hyperactive immune system in these." (PMID 22506061, 2012). "However, in some experiments, up to 30% of AIRE−/− mice remained tumour-free while all AIRE+/+ mice developed tumours." (PMID 22506061, 2012). "Consistently, AIRE, the key molecule for the negative selection of T cells, was not expressed in the major subsets of tumor cells in type 2 TETs." (PMID 36115836, 2022). "Firstly, we profiled the transcript levels of major tumor microenvironment cytokines IL-6, IL-10, tumor necrosis factor-α (TNF-α), and transforming growth factor-β (TGF-β) in PC3 cells in both conditions: with ectopically expressed AIRE and AIRE knockdown." (PMID 29795364, 2018). "In contrast, when mice were primed with 107 lethally irradiated B16F10 tumour cells 4 weeks prior to challenge with live tumour cells, up to 80% of AIRE−/− mice remained tumour–free as opposed to only 20% of AIRE+/+ animals." (PMID 22506061, 2012). "Instead, AIRE+ cells were scattered throughout the tumor tissues like normal thymus." (PMID 36912123, 2023). "Taken together we cannot exclude that AIRE may influence regulatory T cell development, however, the tumour rejection by AIRE−/− mice cannot be solely explained by the lack of functional regulatory T cells." (PMID 22506061, 2012). "In particular, a distorted tumor architecture and low expression of MHC class II on neoplastic cells was observed as well as the absence of the autoimmune regulator (AIRE) gene and a reduced production of T -regulatory (Treg) cells." (PMID 36059463, 2022).
cancer (7 papers, 2016 to 2026). A tumor composed of atypical neoplastic, often pleomorphic cells that invade other tissues. "Through its global transcriptional activation, AIRE might assist cancer-associated gene expression and thus promote the cancer phenotype." (PMID 32012175, 2020). "AIRE is upregulated in OSCC and promotes the expression of cancer-related genes, at least in part by functional interaction with ETS1." (PMID 32012175, 2020).
autosomal recessive disease (5 papers, 2012 to 2022). Autosomal recessive form of disease. "Our data suggests a higher risk for some autosomal recessive diseases in Acadians, notably those associated with AIRE, BCHE, ETFDH, RAPSN and SLC17A5 (2 variants)." (PMID 35488281, 2022).
genetic disorder (5 papers, 2020 to 2024). "Although APECED is a genetic disease due to the loss of AIRE, a central tolerance regulator, the disease’s components involve T and B cells responsible for tissue damage." (PMID 35167497, 2022).
endocrinopathies (4 papers, 2022 to 2023). "All had biallelic mutations in the autoimmune regulator gene and in addition to endocrinopathies, also significant bone fragility." (PMID 36944707, 2023). "APS1 is caused by mutations in the autoimmune regulator (AIRE) gene, resulting in the loss of thymic deletion of autoreactive T cells with multiple autoimmune features such as endocrinopathies as a result." (PMID 38203686, 2023).
bacterial infection (1 paper, 2022). "Although 94 predicted upstream regulators were conserved amongst the studies, 14 were found only in the endometrium of pregnant healthy cows, and 5 were found only in cows following bacterial infection, including AIRE, NFKBIA, and DUSP1." (PMID 35358206, 2022).
AIRE also shares sentences with these, for which no sentence is quoted: primary immunodeficiency (6 papers); diabetes (4); infection (3); lymphopenia (3); thymic carcinoma (3); Hashimoto thyroiditis (2); hyper-IgE syndrome (2); Hypocalcemia (2); hypogonadism (2); Omenn syndrome (2); Sjögren's syndrome (2); adenitis (1); amyopathic dermatomyositis (1); anemia (1); anterior uveitis (1); autoimmune enteropathy (1); autoimmune gastritis (1); autoimmune lymphoproliferative syndrome (1); autoimmune pancreatitis (1); B cell lymphomas (1); benign tumors (1); breast tumors (1); bronchopulmonary dysplasia (1); cerebral cavernous malformation (1); chondrosarcoma (1); choroiditis (1); colon tumor (1); colorectal tumor (1); combined immunodeficiency (1); cone dystrophy (1).
A further 33 diseases each share a sentence with AIRE in 1 paper.